CLPS (colipase)
Description:
Colipase is a cofactor of pancreatic lipase. It allows the lipase to anchor itself to the lipid-water interface. Without colipase the enzyme is washed off by bile salts, which have an inhibitory effect on the lipase. Enterostatin has a biological activity as a satiety signal.
Tractability: Antibody: UniProt places it where antibodies can reach, with high confidence; its Gene Ontology location is reachable by antibodies, with high confidence; UniProt predicts a signal peptide or a membrane-spanning region.
Gene: Protein-coding gene on chromosome 6 (35,794,982 to 35,798,251, reverse strand). Ensembl gene ENSG00000137392.
Subcellular location: Secreted
Pathways (Reactome):
Digestion and absorption: Digestion of dietary lipid
Sensory Perception: Retinoid metabolism and transport
Gene Ontology:
Molecular function: enzyme activator activity; lipase binding
Biological process: lipid metabolic process; digestion; lipid catabolic process; retinoid metabolic process
Cellular component: extracellular region
Genetic constraint (gnomAD): Loss-of-function variants: 9 observed, 10.99 expected, observed/expected ratio (o/e) 0.82, 90% interval 0.49 to 1.42. The upper end of that interval is the gene's LOEUF score, 1.42, which puts it in group 5 of 6, group 1 being the genes least tolerant of losing a copy. Missense variants: 144 observed, 149 expected, observed/expected ratio (o/e) 0.97, 90% interval 0.84 to 1.11. Synonymous variants: 61 observed, 56.53 expected, observed/expected ratio (o/e) 1.08, 90% interval 0.88 to 1.34.
Homologues: Orthologues: chimpanzee CLPS (100% identical), macaque CLPS (90% identical), dog CLPS (79% identical), rabbit CLPS (79% identical), pig CLPS (77% identical), mouse Clps (76% identical), rat Clps (71% identical), guinea pig CLPS (67% identical), tropical clawed frog clps (49% identical). Paralogues in human: CLPSL1 (30% identical), CLPSL2 (22% identical), LRCOL1 (21% identical).
Diseases named in the same sentence as CLPS in open-access papers:
CLPS is named in the same sentence as 21 diseases in open-access papers, as found by Europe PMC text mining. Sharing a sentence is not in itself a finding about the gene and the disease. The quoted sentences say what the papers report.
breast carcinoma (1 paper, 2019). "Furthermore, high CLPs expression in tumors after neoadjuvant chemotherapy was associated with increased risk of distant metastasis in breast cancer." (PMID 31238895, 2019).
lymphopenia (1 paper, 2017). Reduction in the number of lymphocytes. "The complete absence of CLPs in SOD1G93A at P120 could explain the lymphopenia observed in spleen by other authors at the terminal stage in the murine model, as CLPs are the progenitor source of mature lymphocytes." (PMID 28886177, 2017).
parasitic infection (1 paper, 2023). "CLPs expression upregulated in Drosophila following injury, parasitic infection and bacterial infection by inducing clot formation and wound healing." (PMID 38274813, 2023).
peritonitis (1 paper, 2024). Inflammation of the peritoneum (tissue that lines the abdominal wall and covers most of the organs in the abdomen). "The results showed that OA or inosine alone hardly affected cLPS-induced systemic inflammation and MSU crystal-induced peritonitis, as well as plasma sUA levels and whole blood NAD+ metabolism under inflammatory conditions." (PMID 39527634, 2024).
tuberculosis (1 paper, 2018). A chronic, recurrent infection caused by the bacterium Mycobacterium tuberculosis. "However, future work will be needed to clarify whether ClpS-overexpression in mycobacteria represents a viable resistance mechanism against these novel anti-tuberculosis drugs." (PMID 30463272, 2018).
infection (1 paper, 2014). The state of being infected such as from the introduction of a foreign agent such as serum, vaccine, antigenic substance or organism. "To confirm whether CLPs were within the LSKint population during infection, we examined whether LSKint cells could selectively reconstitute irradiated hosts to generate lymphocyte populations." (PMID 24825601, 2014).
CLPS also shares sentences with these, for which no sentence is quoted: cancer (2 papers); pancreatic carcinoma (2); pancreatitis (2); tumor (2); bacterial infection (1); colorectal cancer (1); cystic fibrosis (1); gastric cancer (1); gout (1); heart failure (1); hepatoma (1); insulinoma (1); Obesity (1); ovarian carcinoma (1); Shwachman-Diamond syndrome (1).